PARG (poly(ADP-ribose) glycohydrolase)
Diseases named in the same sentence as PARG in open-access papers (continued):
Sharing a sentence is not in itself a finding about the gene and the disease.
cancer (continued). "This study suggested that PARG could be an attractive interventional target for BaP induced cancer." (PMID 27003318, 2016). "Thus, we propose a PARG-siRNA utilizing gene-therapy for cancer treatment." (PMID 23467693, 2013). "Therefore, although we have shown that inhibition of both PARP-1 and PARG does not increase cell death in HeLa cells, we have further shown that PARG inhibition may provide an innovative strategy to treat specific types of cancer." (PMID 23254695, 2013). "The inhibition of PARG function in these cancer cells may lead to protective effects." (PMID 23254695, 2013). "PARG and PARP have been reported to localize to sites of DNA damage and, intriguingly, mice deficient in PARG are hypersensitive to both -irradiation and alkylating agents, suggesting that high levels of PARG may contribute to resistance to DNA-damaging agents in cancer therapy." (PMID 20195492, 2010). "A subset of cancer cells are intrinsically sensitive to inhibitors targeting PARG, the poly(ADP-ribose) glycohydrolase that degrades PAR chains." (PMID 39015544, 2024). "Despite the importance of PARP1/2 inhibitors (PARPis) in cancer treatment and the growing interest in PARG as a therapeutic target, the relative contribution of TARG1 and PARG in the modulation of ADPr levels and cellular homeostasis remains to be elucidated." (PMID 37676774, 2023). "However, the resistance of cancer to PARG inhibitors and its resistance mechanism remains unclear." (PMID 36053937, 2023). "Altogether, our data identify TARG1 as a potential biomarker for the response of cancer cells to PARP and PARG inhibition and establish that the interplay of TARG1 and PARG protects cells against genomic instability." (PMID 37676774, 2023). "Therapeutic advances to exploit metabolic vulnerabilities via Poly(ADP-ribose) glycohydrolase (PARG), which catalyzes the oligomerization of the essential cofactor NAD+, are being explored in IDH-mutant cancers." (PMID 35877430, 2022). "It was shown in numerous reports that many cancer cells exhibit high level of PARP1 and pADPr, which is frequently cooperate with lower PARG level." (PMID 35585513, 2022). "The selective and enhanced PAR-induced cellular lethality following co-treatment of a PARG inhibitor with NRH can feasibly result from either enhanced global DNA damage and/or enhanced replication stress in cancer cells, both known to activate PARP1." (PMID 34806016, 2021). "Despite the clear therapeutic potential for ARH3 and PARG as drug targets and biomarkers for cancer cell sensitivity to PARP and PARG inhibition, implementation of these strategies in clinics currently faces significant challenges." (PMID 34019811, 2021). "Altogether, our results highlight the high potential of ARH3 both as a drug target and as a predictive biomarker for cancer cell sensitivity to PARP and PARG inhibition." (PMID 34019811, 2021). "Altogether, our data highlight the potential for ARH3 as a novel drug target and a biomarker for cancer cell sensitivity to PARP and PARG inhibition." (PMID 34019811, 2021). "Therefore, PARG may be considered both a tumor suppressor and a therapeutic target of cancer." (PMID 32344695, 2020). "Overall, we demonstrate for the first time that elevated PARG activity is oncogenic and modulates SMAD activity, and we propose that PARG represents a potent target for anti-cancer therapy." (PMID 30459355, 2019). "Because RBP functions can be regulated by manipulating the activities of PARP and PARG, PARP1 and PARG inhibitors are potential therapeutics to treat a variety of RBP-related cancer and neurodegenerative diseases." (PMID 23921685, 2013). "Genetic depletion of PARG or inhibition of PARG strongly increased the level of DNA damage induced by TMZ, methyl methanesulfonate (MMS), ionizing radiation (IR), or cisplatin and significantly reduced cell survival in different types of cancer cells." (PMID 35892832, 2022).
cancer (continued). "We thus propose that combined PARG inhibitor and CHK1 inhibitor therapy might serve as a novel therapeutic strategy in cancer." (PMID 34197606, 2021). "The deletion or inhibition of eraser enzymes such as PARG may be used to potentiate the synthetic lethality drugs in cancers with mutant phenotypes., and for PARP inhibitor-resistant cancers or to sensitize cancer chemo- and radiotherapy." (PMID 34639169, 2021). "We summarize how aberrant alterations of PARG, NAMPT, NQO1, cMET and “BRCAness” genes that have been shown to affect PARP activity in cancers could serve as prognostic biomarkers for targeted therapy." (PMID 32295316, 2020). "Using cancer cell lines genetically deficient in BRCA1 and/or PTEN and siRNA-mediated depletions, our study shows that PARG deficiency is neither synthetic lethal with BRCA1 nor with PTEN deficiency." (PMID 27375368, 2016). "Thus, this study provides important insight into optimizing the chemotherapeutic strategies designed to improve the treatment of cancer patients via the targeting of PARP-1 and PARG." (PMID 23254695, 2013). "In addition, we discuss the potential of PARP and PARG inhibitors for the treatment of RBP-related human diseases, including cancer and neurodegenerative disorders." (PMID 23921685, 2013). "Each has been previously individually evaluated in chemotherapy, but the effects of combination PARP-1 and PARG inhibition in cancer cells are not known." (PMID 23254695, 2013). "Chen and Yu described the possibility of using COH34, a poly(ADP-ribose) glycohydrolase inhibitor, as a potentiator of CDDP, doxorubicin, temozolomide, and camptothecin against a wide panel of cell lines representing various types of human cancers, including PEO1/4." (PMID 37886943, 2023). "Potent PARG inhibitors (PARGis) have been developed (PDD00017273 and JA2131) that show promise when combined with irradiation but are minimally effective (against ovarian cancer cells) as a single agent unless targeted to cancers with replication defects or combined with CHK1 inhibitors." (PMID 34806016, 2021). "The involvement of PARG in cancer development has not been extensively studied." (PMID 32344695, 2020). "Overall, based on the pro-tumorigenic effects of PARG activity, and the profound effect of PARG knockdown on tumor growth and metastasis, our data emphasize the potential of PARG inhibition as a rational approach to drugging the PAR pathway, beyond PARP1/2 inhibition, for anti-cancer therapy." (PMID 30459355, 2019). "When using SNVs only, most such genes were known cancer genes, such as U2AF1, IDH1, and DNMT3A in LAML (FLT3 SNVs cluster within five amino acids), AKT1 and KRAS in BRCA, BRAF and KRAS in COADREAD, IDH1 and PARG (poly (ADP-ribose) glycohydrolase) in GBM, and KRAS in UCEC." (PMID 25348067, 2014). "However, it is not known if the targeting of both PARP-1 and PARG in cancer cells can lead to a synergistic increase in cancer cell death." (PMID 23254695, 2013). "As the disruption of PARP-1 or PARG activity leads to the uncoordinated metabolism of PAR, this phenomenon may be required for enhancing the chemo-therapeutic treatment of specific types of cancers." (PMID 23254695, 2013). "Thus, the results indicate that inhibiting both PARP-1 and PARG, which both are chemotherapeutic targets that increase cancer cell death, does not lead to synergistic cell death in HeLa cells." (PMID 23254695, 2013). "Therefore, strategies that target PAR metabolism for the improved treatment of cancer may be required to target PARP-1 and PARG individually in order to optimize cancer cell death." (PMID 23254695, 2013). "Interestingly, PARG activity may be required to maintain telomere length, although this appears to be via homology-directed repair mechanisms that support the alternative lengthening of telomeres (ALT) mechanism used by ∼5–15% of cancer cells." (PMID 39015544, 2024).
cancer (continued). "Thus, although PARG inhibition may be useful for treatment of certain cancers due to their complex etiology, the upregulation of PARG, which may be more straightforward and effective in other cancers, have not been thoroughly studied in vitro and in vivo." (PMID 35585513, 2022). "Accordingly, IDE161 behaved a different profile than PARP inhibitors in a panel of cancer cell lines irrespective of HRD, suggesting different dependency of PARG and PARP in cancers." (PMID 37679326, 2023). "The possible roles of NAD+ synthesis and PAR-degrading enzymes have not yet been investigated as possible targets in cancer even though the effects of PARP1 and PARG inhibition often result in similar rather than opposite outcomes in DNA damage scenarios." (PMID 33922595, 2021). "Cancer-derived cells express an abnormally high level of the PARP-1 protein and no PARG." (PMID 24504413, 2014).
tumor (38 papers, 2009 to 2025). "Lastly, using the online application Kapplan Meier Plotter31 we observed that low PARG gene expression (data from GEO datasets) in stage IV CRC tumours was associated with improved OS in patients." (PMID 41451844, 2025). "Together, our findings strongly suggest FEN1 and EXO1 to be useful as pharmaceutical targets for PARG-deficient tumor cells, as well as for the optimization of PARGi in precision oncology." (PMID 38360994, 2024). "PARP1 and PARP2 transcript levels were significantly higher in Tumor than Peri-Tumor and control tissues with PARG transcripts higher in all except NASH-associated Tumor tissues." (PMID 35804458, 2022). "A recent study proposed that loss of PARG activity is a possible mechanism for PARPi resistance in BRCA2 deficient tumours." (PMID 33674744, 2021). "This inhibition of PARG then led to an increase in the autoPARylation of PARP1, which was consistent with the loss of PARG restoring the PAR formation on PARP1 that conferred resistance to PARP inhibition in BRCA2-deficient tumor cells." (PMID 32483468, 2020). "Our study shows that although some tumour cells display slight sensitivity to PARG deficiency, this sensitivity cannot be correlated to BRCA1- or PTEN- deficiency." (PMID 27375368, 2016). "In this report, our results showed that PARG silencing significantly inhibited colony formation and cell migration induced by BaP, and suppressed tumor formation caused by BaP-induced cell transformation in nude mice." (PMID 27003318, 2016). "Previous studies have reported that Inhibition of PARG can lead to cell death in BRCA2-deficient tumor cells." (PMID 27003318, 2016). "In contrast, PARG-depletion was shown to sensitize tumour cells to genotoxic insult caused by ionizing radiations and mild but not severe concentrations of alkylating agents or hydrogen peroxide." (PMID 27375368, 2016). "PARG depletion is associated with PARPi resistance in HRD tumours by restoring PARP1 signalling." (PMID 39796639, 2024). "Therefore, PARG depletion cannot be considered as a strategy to kill tumour cells mutated in BRCA1 or PTEN." (PMID 27375368, 2016). "Therefore, PARG depletion cannot be considered as a strategy to kill tumours cells mutated in BRCA1 or PTEN." (PMID 27375368, 2016). "Lastly, consistent with PARG involvement in SSBR, it was reported recently that depletion of PARG activity, using either siRNA or the reported PARG inhibitor Gallotannin, in tumour cells deficient in the homologous recombination repair pathway resulted in selective sensitisation." (PMID 23251397, 2012). "Importantly, in previous studies, we found that PARG deficiency causes PARPi resistance in human BRCA2-deficient tumor cells and may contribute to PARPi resistance in patients." (PMID 38360994, 2024). "Although further testing is needed to validate findings in other cellular backgrounds and in pre-clinical studies, our data do suggest that the future development of clinically applicable PARG inhibitors may hold promise for treatment of some types of HRR-deficient tumours." (PMID 28254358, 2017). "In addition, PARG deficiency sensitizes tumor cells to chemo- and radiation therapies." (PMID 27003318, 2016). "PARG facilitates cell transformation and invasion in several tumor models, establishing that the DePARylation levels are required in S phase progress, so much so that its inhibition leads to cycle arrest and cell death." (PMID 41463260, 2025). "Biochemically, the combination of PARG inhibition and PARPi resistance models focus on basic aspects of the tumor, such as mitochondrial dynamics, ER/mitochondria interactions, and the use of lipids as fuel to adapt to oxidative stress or anaerobic glycolysis." (PMID 41463260, 2025). "Immunohistochemical analysis of 170 CRC patient tumours revealed that positive PARG expression correlated with poor response to 5FU + Irinotecan, increased liver metastases, and worse long‐term survival." (PMID 41451844, 2025).
tumor (continued). "PARP and PARG inhibitors exacerbate such tumor vulnerabilities, resulting in increased DNA damage and the accumulation of unresolved replication intermediates that cause replication and mitotic catastrophe." (PMID 38360994, 2024). "(f) Left: Representative images of PARG IHC staining in breast and ovarian tissues and tumor samples to determine the PARG expression level." (PMID 38578205, 2024). "PARG-S26A significantly increased the tumor size and weight compared to WT, suggesting that upregulated c-Myc in S26A cells promotes HCC." (PMID 37858678, 2023). "We found that the overexpression of PARG in mouse allografts produces significantly smaller tumors with a delay in tumor onset." (PMID 35585513, 2022). "The involvement of PARG in suppression of tumor angiogenesis is supported by the observation that, in contrast to its effect on many chemokine genes, hPARG expression upregulates ADGRG1 gene 8-fold." (PMID 35585513, 2022). "Previously, we have demonstrated that ccRCC cell exhibit lower level of PARG compare to untransformed cells and PARG overexpression results in the similar anti-tumor effect." (PMID 35585513, 2022). "In BRCA2‐deleted tumours, PARPi resistance can be triggered by loss of the poly(ADP‐ribose) glycohydrolase PARG." (PMID 35107878, 2022). "Tumours with high polβ/PARG co-expression have poor PFS (p = 0.041) as well as OS (p = 0.045) compared to tumours with low polβ/PARG co-expression." (PMID 33674744, 2021). "Low PARG expression was seen in 60/274 (22%) tumours and high PARG expression was observed in 214/274 (72%) of tumours." (PMID 33674744, 2021). "In standard culture conditions, ovarian commercial and tumor-derived cell lines showed different expression levels of PARG protein and noticeably, the BRCA1 protein was at a very low level in SNU251 cells." (PMID 34778062, 2021). "Our work supports the idea that reduction of pADPr level and PARP-1 activity is also critical for anti-tumor effects as the PARG overexpression approach demonstrated similar phenotype." (PMID 34638458, 2021). "Collectively, elevated expression of wild-type PARG in HMLEN increased tumor initiation rate and accelerated tumor growth in this ER-negative model, consistent with the role of PARG as an oncogene." (PMID 30459355, 2019). "Database analysis of sequencing data from The Cancer Genome Atlas (TCGA) revealed that PARG is overexpressed across numerous tumor types." (PMID 30459355, 2019). "In vivo, we find that PARG cooperates with the HER2 oncogene to promote tumor initiation and outgrowth." (PMID 30459355, 2019). "HMLEN cells have a limited capacity to initiate tumors in vivo, and hence this represented an ideal model to examine the capacity of PARG to influence tumor initiation or outgrowth." (PMID 30459355, 2019). "While the PARG knockdown tumors often grew to palpation in these experiments, we consistently observed that MDA-MB-231 cells depleted of PARG were significantly delayed in tumor outgrowth." (PMID 30459355, 2019). "Based on these studies, and other reports showing glycolytic flux is required for HER2-driven tumor growth, we propose that potentiating energy production represents another mechanism whereby PARG acts as an oncogene." (PMID 30459355, 2019). "The number of macroscopic surface metastases on the lungs of the PARG-depleted group was strikingly decreased with a median value of 3 metastases per lung compared to 20 tumor nodules on the lungs in the control group." (PMID 30459355, 2019). "Numerous in vitro studies showed that PARG depletion sensitized tumor cells to chemotherapy, radiation and DNA damaging agents, highlighting its therapeutic potential, but without translating this knowledge to relevant in vivo models." (PMID 30459355, 2019).